CYP7B1 (cytochrome P450 family 7 subfamily B member 1)
Diseases named in the same sentence as CYP7B1 in open-access papers (continued):
Sharing a sentence is not in itself a finding about the gene and the disease.
diabetes (4 papers, 2021 to 2025). "Insulin resistance has been shown to downregulate expression of Cyp7b1 in the mice with diabetes." (PMID 33252713, 2021). "However, in a subgroup analysis of patients without diabetes (n = 58), CYP7B1-positive expression was positively associated with BCR (age-adjusted HR: 1.775; CI: 1.001–3.169, p = 0.05)." (PMID 38731981, 2024). "In diabetes and NAFLD, reduced hepatic CYP7B1 expression has been reported, suggesting a role of the alternative pathway for metabolic homeostasis in humans." (PMID 33252713, 2021). "These facts let us hypothesize that the absence of CYP7B1 in rats may be translated in diabetes or prediabetes alterations." (PMID 41465421, 2025). "However, recent studies have proven otherwise as intracellular insulin paucity (characteristic of both type 1 and 2) is what leads to low levels of CYP7B1 and the accumulation of toxic cholesterol metabolites, explaining the existence of MASLD progression with both types of diabetes." (PMID 38591148, 2024). "Although controversial, these data may justify the finding of our study that revealed a higher risk of biochemical recurrence among individuals with higher levels of CYP7B1 expression in a subgroup analysis of patients without diabetes (HR = 1.78)." (PMID 38731981, 2024).
Hepatic fibrosis (4 papers, 2018 to 2022). The presence of excessive fibrous connective tissue in the liver. "The mRNA expression levels of key enzymes in classical or alternative BA synthesis pathways, Cyp7a1 and cytochrome P450 family 7 subfamily B member 1 (Cyp7b1), were significantly increased in the moderate liver fibrosis stage and tended to increase in the advanced fibrosis stage." (PMID 35637968, 2022). "These patients lacking CYP7B1 activity are characterized by elevated levels of 24-HC, 25-HC, 27-HC, 3β-hydroxy-5-cholenoic and 3β-hydroxy-5-cholestenoic acids, aggressive hepatic fibrosis and inflammation that eventually lead to liver failure and premature death." (PMID 34685636, 2021).
Hypercholesterolemia (4 papers, 2021 to 2023). An increased concentration of cholesterol in the blood. "CYP7B1 is a neuronal enzyme involved in 27-OHC catabolism, decreased activity of which was shown in the case of hypercholesterolemia, oxidative stress, inflammation, etc., to be a possible explanation for the increased 27-OHC." (PMID 35457188, 2022).
liver failure (4 papers, 2021 to 2025). A liver disease characterized by the liver losing or has lost all of its function. "The same is true for a potential liver-specific gene therapy for the treatment of severe neonatal liver failure in homozygous CYP7B1 mutation carriers." (PMID 40741602, 2025). "Most reported patients with CYP7B1 mutations presenting with liver disease in infancy have died of liver failure." (PMID 33849447, 2021). "Most patients with CYP7B1 deficiency presenting with liver disease in infancy succumb to liver failure in early life." (PMID 33849447, 2021). "Abnormal expression of CYP7B1 may lead to neonatal liver failure and progressive neurodegeneration in adults." (PMID 40433364, 2025).
steatosis (4 papers, 2019 to 2024). Increased lipid within the cytoplasm of cells. "Since steatosis has been associated with induction of the acidic BA synthetic pathway, we studied the expression of STAR (Star), 25-hydroxycholesterol 7-alpha-hydroxylase (Cyp7b1) and sulfotransferases 2a1 and 3a1 (Sulf2a1 and Sulf3a1)." (PMID 33374541, 2020). "Of note, Cyp7b1 expression was strongly and inversely correlated with steatosis in the control/MCD groups." (PMID 33374541, 2020). "However, the downregulation of Cyp7b1 in this pathway, which is typically found in steatosis, results in the accumulation of oxysterol intermediaries, which have important inflammatory and regulatory effects." (PMID 33374541, 2020). "Recent publications aiming at the identification of hepatic transcriptomic signatures distinguishing simple steatosis from NASH did not report differential mRNA expression of CYP7B1 when comparing these groups." (PMID 34685636, 2021).
Alzheimer disease (3 papers, 2019 to 2021). A progressive, neurodegenerative disease characterized by loss of function and death of nerve cells in several areas of the brain leading to loss of cognitive function such as memory and language. "Consistently, Ad-MAFG infection decreased the luciferase activities of the reporters containing Cyp7b1, Cyp8b1, and Cyp27a1 promoters in hepatocytes, respectively." (PMID 33754066, 2021). "Sleep start is also associated with one SNP at gene CYP7B1 related to BMI, two SNPs near gene HSD17B12 related to BMI, two SNPs near MIR129-2 also related to BMI and Alzheimer’s Disease, and two SNPs near LOC101928944 related to schizophrenia." (PMID 33075057, 2020). "CYP7B1 is expressed in human hippocampus and interestingly CYP7B1 mRNA is significantly reduced in dentate neurons from Alzheimer’s disease subjects." (PMID 31013940, 2019).
colitis (3 papers, 2018 to 2022). Inflammation of the colon. "Accordingly, there was a significant correlation between CH25H and CYP7B1 expression and colonic inflammation (as measured by CXCL8 expression) in humans with ulcerative colitis." (PMID 29343433, 2018). "This group also detected increased Gpr183, Ch25h and Cyp7b1 expression in the acute and chronic DSS colitis models, but they did not observe an effect of Gpr183 or Ch25h gene deficiency on inflammation severity." (PMID 36389671, 2022).
colon cancer (3 papers, 2019 to 2022). "In colon cancer, miR-17 induced epithelial-mesenchymal transition and the formation of a stem cell-like population through the modulation of CYP7B1 expression." (PMID 35536524, 2022). "Simultaneously, miR-17 was also proved to induce EMT process by regulating CYP7B1 expression in colon cancer." (PMID 32742189, 2020).
dyslipidemia (3 papers, 2019 to 2021). "Strikingly, a similar decrease in Cyp7b1 mRNA expression as well as an increase in 25-OHC level have also been reported in the liver of both ob/ob and db/db mice, strengthening the fact that the dysregulation of hepatic MyD88 might be involved in metabolic syndrome." (PMID 31039009, 2019).
gallstones (3 papers, 2018 to 2025). Solid crystalline precipitates in the biliary tract, usually formed in the gallbladder, resulting in the condition of cholelithiasis. "On the other hand, it may suppress bile acid synthesis enzymes (e.g., CYP7B1), reducing bile acid levels, resulting in excess cholesterol in the bile and encouraging the development of gallstones." (PMID 41287115, 2025). "Simultaneously, it suppresses bile acid synthase (e.g., Cyp7b1) expression and interferes with the farnesoid X receptor (FXR) pathway, thus altering the bile salt composition in a manner that favors gallstone formation." (PMID 39944962, 2025). "CYP7A1, CYP7B1, LXR, and HMGCR mRNA may be efficient targets of YCHD, which may be a preventive drug to reverse liver injury, normalize bile lipids, facilitate gallstone dissolution, and attenuate gallstone formation." (PMID 30310412, 2018).
liver disease (3 papers, 2015 to 2021). "Increased Cyp27a1 and Cyp7b1 mRNA levels are indicative of a functional upregulation of the alternative pathway to reduce hepatotoxicity and the progression of liver disease to NASH37." (PMID 26619823, 2015). "Extrahepatic bile acid synthesis is not a new concept; cyp7b1 is expressed in many tissues and is important for supplementing bile acid production during liver disease." (PMID 29965978, 2018).
osteoarthritis (3 papers, 2021 to 2025). A noninflammatory degenerative joint disease occurring chiefly in older persons, characterized by degeneration of the articular cartilage, hypertrophy of bone at the margins and changes in the synovial membrane. "Presumably, hydroxylated cholesterol derivatives, in particular, are involved in the pathogenesis of OA, since adenoviral overexpression of CH25H or CYP7B1 in mouse chondrocytes has previously been found to cause experimental osteoarthritis." (PMID 41296055, 2025). "Adenoviral overexpression of Ch25h or Cyp7b1 in mouse joint tissues caused experimental osteoarthritis, whereas knockout or knockdown of these hydroxylases abrogated the pathogenesis of osteoarthritis." (PMID 38104944, 2024). "Retinoic acid-related orphan receptor α (RORα) was found to mediate the induction of osteoarthritis by alterations in cholesterol metabolism, which acts as downstream receptor of cholesterol hydroxylases, including cholesterol 25-hydroxylase (CH25H) and 25-hydroxycholesterol 7α-hydroxylase (CYP7B1)." (PMID 34149433, 2021).
Spastic paraplegia (3 papers, 2019 to 2023). Complete loss of the ability to move the lower limbs accompanied by spasticity of the lower limbs. "In spastic paraplegia caused by CYP7B1 mutations, two short-term phase II clinical trials have shown that atorvastatin can reduce levels of oxysterols which lead to neurotoxicity in that disorder." (PMID 37119330, 2023). "In humans, deficiency in CYP7B1 leads to SPG5, a form of spastic paraplegia, defined by progressive neurodegeneration of corticospinal tract motor neurons." (PMID 31013940, 2019).
acute myeloid leukemia (2 papers, 2016 to 2022). Acute myeloid leukemia (AML) is a group of neoplasms arising from precursor cells committed to the myeloid cell-line differentiation. "We first explored the overall survival of acute myeloid leukemia (AML) patients based on relative levels of CYP7B1 expression from TCGA." (PMID 36316327, 2022). "Moreover, acute myeloid leukemia (AML) patients with high CYP7B1 expression (expected to have inhibition of 27HC) had significantly shorter survival than those with low CYP7B1 expression (expected to have an elevation of 27HC)." (PMID 36316327, 2022).
breast tumors (2 papers, 2020 to 2023). "CYP7B1 expression has been shown to be lower in ERα-positive breast tumors, relative to normal breast tissue, and associated with better prognosis." (PMID 32075687, 2020). "The Cancer Genome Atlas data analysis showed that CYP27A1 levels are more or less similar in breast tumours and normal breast tissues, whereas the CYP7B1 expression is significantly lower in breast tumours." (PMID 37614064, 2023). "Specifically, CYP7B1 was 50% lower in ER+ tumor tissue relative to normal tissue suggesting lower CYP7B1 may be responsible for the elevated 27HC observed in breast tumors." (PMID 32075687, 2020). "However, one study suggests similar expression of CYP27A1 but markedly different CYP7B1 in normal vs. breast tumor tissue." (PMID 32075687, 2020).
Cirrhosis (2 papers, 2012 to 2025). A chronic disorder of the liver in which liver tissue becomes scarred and is partially replaced by regenerative nodules and fibrotic tissue resulting in loss of liver function. "Genes involved in cirrhosis development (ABCG2, CTNNB1, B2M, IFNAR1, IFNAR2), and hepatic cholestasis (CYP7B1) were found significantly down-regulated in patients without HCC." (PMID 22792259, 2012).
colorectal cancer (2 papers, 2016 to 2026). A primary or metastatic malignant neoplasm that affects the colon or rectum. "Immunostaining for CYP7B1 in primary tumours showed the highest proportion of strong immunostaining, with 62.8% of primary colorectal cancers displaying strong immunoreactivity for this target protein." (PMID 27341022, 2016). "The intensity of immunostaining was significantly higher in primary colorectal cancer compared with normal colonic mucosa for CYP2R1 (p<0.001), CYP7B1 (p<0.001), CYP8B1 (p<0.001), CYP46A1 (p<0.001) and CYP51A1 (p=0.001)." (PMID 27341022, 2016). "Immunohistochemistry was performed on a colorectal cancer tissue microarray containing 650 primary colorectal cancers using monoclonal antibodies to CYP2R1, CYP7B1, CYP8B1, CYP27A1, CYP39A1, CYP46A1 and CYP51A1, which we have developed." (PMID 27341022, 2016). "This study has profiled the expression of the cholesterol metabolising enzymes CYP2R1, CYP7B1, CYP8B1, CYP27A1, CYP39A1, CYP46A1 and CYP51A1 in primary colorectal cancer tissue using a well-characterised cohorts of colorectal cancers." (PMID 27341022, 2016). "CYP2R1, CYP7B1, CYP8B1, CYP46A1 and CYP51A1 all showed significantly increased expression in primary colorectal cancer compared to normal colonic mucosa with CY7B1 demonstrating the highest proportion of strong immunoreactivity in colorectal cancer compared to all other enzymes studied." (PMID 27341022, 2016).
hereditary spastic paraplegia (2 papers, 2017 to 2021). Hereditary spastic paraplegias (HSP) comprise a genetically and clinically heterogeneous group of neurodegenerative disorders characterized by progressive spasticity and hyperreflexia of the lower limbs. "Hereditary spastic paraplegia (HSP) gene analysis identified the compound heterozygous mutations c.825T>A (pTyr275*) and c.1193C>T (pPro398Leu) in CYP7B1 gene." (PMID 34946825, 2021).
intrahepatic cholestasis (2 papers, 2021 to 2023). A cholestasis characterized by impairment of the bile flow caused by obstruction located in the liver. "Deficiency of oxysterol 7α-hydroxylase, encoded by CYP7B1, is associated with fatal infantile progressive intrahepatic cholestasis and hereditary spastic paraplegia type 5." (PMID 33849447, 2021).
motor neuron disease (2 papers, 2019). "Hereditary spastic paraplegia type 5 (SPG5), like ALS, is a form of motor neuron disease, but unlike ALS, it is a monogenic disease resulting from a deficiency in CYP7B1 (cytochrome P450 family 7 subfamily B member 1), the oxysterol 7α-hydroxylase." (PMID 30936243, 2019). "The concentrations of non-esterified 26-HC and 3β-HCA in human plasma/serum are considerably greater than those in the Cyp7b1-/- mouse, and this may explain the presence of a motor neuron disease phenotype in SPG5 patients but not in the Cyp7b1-/- mouse." (PMID 31013940, 2019).
pulmonary arterial hypertension (2 papers, 2018 to 2024). Pulmonary arterial hypertension (PAH) is a group of diseases characterized by mean pulmonary artery pressure >20 mmHg and elevated pulmonary arterial resistance leading to right heart failure. "Also, cyp7b1 has recently been identified in human lungs as a biomarker for the development of pulmonary arterial hypertension." (PMID 29965978, 2018).
type 2 diabetes (2 papers, 2021 to 2024). "In mice with type 2 diabetes, decreased CYP7B1 mRNA expression has been observed." (PMID 39679283, 2024). "Interestingly, the alternative bile acid synthesis pathway seems to be differentially altered in metabolic-related disorders, since CYP7B1 has been described as decreased in murine models as well as patients with type 2 diabetes but was found elevated in patients with progressive MAFLD." (PMID 34685636, 2021).
Arthritis (1 paper, 2014). Inflammation of a joint. "First, a positive correlation was shown between increased CYP7B1 mRNA/CYP7B1 enzyme activity and the progression (severity) of murine arthritis." (PMID 24586766, 2014).
Autoimmunity (1 paper, 2017). The occurrence of an immune reaction against the organism's own cells or tissues. "Moreover, in EAE, expression of EBI2 receptor in Th17 cells, CH25H in microglia and CYP7B1 in infiltrating immune cells have been found to be increased demonstrating EBI2/oxysterol role as a mediator of autoimmunity and inflammation." (PMID 29246262, 2017).
bipolar disorder (1 paper, 2023). A disorder of the brain that causes unusual shifts in mood, energy, activity levels and the ability to carry out day-to-day tasks. "DEGRE classifies the CYP7B1 gene expression profile as upregulated in patients with bipolar disorder compared to healthy individuals (log2 fold-change = 0.24)." (PMID 37033732, 2023).
bladder cancer (1 paper, 2025). "Many CYPs were also significantly inversely correlated with GHR expression in male patients with bladder cancer, and CYP7B1 was downregulated with increased GHR expression in both sexes." (PMID 40806252, 2025).
cerebrotendinous xanthomatosis (1 paper, 2023). Cerebrotendinous xanthomatosis (CTX) is an anomaly of bile acid synthesis characterized by neonatal cholestasis, childhood-onset cataract, adolescent to young adult-onset tendon xanthomata, and brain xanthomata with adult-onset neurologic dysfunction. "Biallelic mutations in CYP27A1 and CYP7B1, two critical genes regulating cholesterol and bile acid metabolism, cause cerebrotendinous xanthomatosis (CTX) and hereditary spastic paraplegia type 5 (SPG5), respectively." (PMID 37024986, 2023).
Crohn disease (1 paper, 2022). A gastrointestinal disorder characterized by chronic inflammation involving all layers of the intestinal wall, noncaseating granulomas affecting the intestinal wall and regional lymph nodes, and transmural fibrosis. "They found that GPR183 mRNA as well as CH25H and CYP7B1 were increased in colon biopsy samples of UC patients vs. healthy controls, although Crohn’s disease patients and responsiveness to TNF blockade were not included in that analysis." (PMID 36389671, 2022).
emphysema (1 paper, 2018). "We clearly show that mice treated with the CYP7B1 inhibitor clotrimazole, resolved iBALT formation, and attenuated CS‐induced emphysema in vivo." (PMID 29674392, 2018). "Finally, inhibition of the oxysterol pathway, using the CYP7B1 inhibitor clotrimazole, resolved B cell‐driven iBALT formation and attenuated CS‐induced emphysema in vivo in a therapeutic approach." (PMID 29674392, 2018). "Finally, inhibition of the oxysterol pathway, using the CYP7B1 inhibitor clotrimazole, resolved iBALT formation and attenuated CS‐induced emphysema in vivo in a therapeutic approach." (PMID 29674392, 2018).
hereditary spastic paraplegia type 5A (1 paper, 2021). "In this regard, patients with hereditary spastic paraplegia type 5A (SPG5) have very high 27-OH levels in their brain due to a mutation in the gene CYP7B1 encoding oxysterol-7α-hydroxylase." (PMID 34449045, 2021).
HIV-1 infection (1 paper, 2015). The type species of lentivirus and the etiologic agent of acquired immunodeficiency syndrome (AIDS). "Among these, two GWASs for HIV-1 infection susceptibility have suggested a role of variants within or in the vicinity of the CYP7B1 gene in this phenomenon." (PMID 26399852, 2015). "Overall, these data indicate that the two GWAS-defined variants in the CYP7B1 region do not strongly influence HIV-1 infection susceptibility." (PMID 26399852, 2015). "Overall, these data lead us to conclude that the two genotyped variants in the CYP7B1 region do not strongly influence HIV-1 infection susceptibility." (PMID 26399852, 2015). "Results, however, did not confirm the previously reported associations, suggesting that these particular CYP7B1 genetic variants do not play a role in HIV-1 infection susceptibility, and indicating that other variants will need to be analyzed." (PMID 26399852, 2015).
hypertriglyceridemia (1 paper, 2025). A laboratory test result indicating elevated triglyceride concentration in the blood. "Cyp7b1-deficient rats are resistant to postprandial hypertriglyceridemia, a common feature with mice expressing human lipoprotein lipase and Apoc3-deficient mice." (PMID 41465421, 2025). "The lack of CYP7B1 decreases the postprandial hypertriglyceridemia response without inducing changes in APOA4 or total and HDL cholesterol." (PMID 41465421, 2025).
hyperuricemia (1 paper, 2025). An abnormally high level of uric acid. "Future research, by specifically detecting the expression and activity of CYP7B1, will be of great significance for comprehensively clarifying the role of alternative pathways in the observed bile acid profile disorder in hyperuricemia." (PMID 41292687, 2025).